IL18 (interleukin 18)
Diseases named in the same sentence as IL18 in open-access papers (continued):
Sharing a sentence is not in itself a finding about the gene and the disease.
depression (continued). "Serum IL-6, IL-8, IL-18, and IFN-γ levels are estimated biomarkers for depression severity in nurses, showing that they may increase the risk of inflammatory dysregulation when nurses have high depressive symptoms." (PMID 37637801, 2023). "Interestingly, IL-1β and IL-18 are significantly increased in patients with MDD, and their levels are associated with the severity of depression." (PMID 37369673, 2023). "However, the demonstrated effect of PGS to evaluate individual liability to depressive personality in the DeprVUR sample is probably attributed to a significant impact of the PCLO rs2715157 and the IL18 rs187238 (p < 0.05) on depression score." (PMID 37510260, 2023). "Further research is needed if only to more precisely assess the role of IL-18 in pregnancy and its relationship to postpartum depression, especially since elevated levels of IL-18 are also observed in individuals with depressive disorders unrelated to pregnancy." (PMID 37892657, 2023). "Interleukin-18 (IL-18) may participate in the development of major depressive disorder, but the specific mechanism remains unclear." (PMID 35931995, 2022). "Furthermore, our prior study demonstrated the involvement of IL-18 in the mechanism for post-stroke depression." (PMID 35931995, 2022). "The level of IL-18 was higher in patients with depression in comparison with healthy controls." (PMID 35931995, 2022). "Pearson correlation analysis of serum IL-18 level and resting-state fMRI imaging using covariates of patient age, gender, and years of education was completed to determine differences at the whole-brain level between depression patients and healthy controls." (PMID 35931995, 2022). "These decreases in regulatory functions may be related to depression-like manifestations – suggesting that IL-18 mediates the pathogenesis of depression through an inflammatory response." (PMID 35931995, 2022). "Prior studies suggest the involvement of IL-18 in depression-like behaviors in mice." (PMID 35931995, 2022). "It has been found recently that IL-1β and IL-18 play an important role in depression." (PMID 35069768, 2022). "Interestingly, BDNF emerged among the genes shared by depression and atherothrombosis, and it was well-connected to all the genes identified in both databases, namely, IL-1β, IL-6, IL-18, TNF, APOE, ACE, MTR, MTHFR genes." (PMID 35911513, 2022). "Thus, IL18 is closely related to neural function and psychiatric phenotypes such as depression as well as the immune system." (PMID 36151082, 2022). "As an important regulator of immune activity, IL-18 has been found to be related to the occurrence of schizophrenia, and may also be involved in the pathogenesis of depression." (PMID 35931995, 2022). "This suggests that abnormal levels of IL-18 in the peripheral blood may interfere with functional brain activity – suggesting a relationship between depression onset and IL-18." (PMID 35931995, 2022). "Furthermore, we explored the possible mechanism of IL-18-mediated depression and interference with depression-related brain activity." (PMID 35931995, 2022). "Then, we identified 16 molecules that might cause the depressive characteristics of Il18−/− mice; in particular, decreased TTR in the PFC might be a mediator for developing depression." (PMID 34708129, 2021). "Therefore, our results suggest that in IL-18-deficit conditions, TTR in the brain is one of the mediators causally related to depression, and AHSG in peripheral organs is one of the regulators inducing energy imbalance." (PMID 34708129, 2021). "Therefore, related research on IL-18 is expected to become another important direction of depression research." (PMID 34526897, 2021). "However, the trigger effects of IL-6 and IL-18 on depression were attenuated in patients receiving statins, suggesting that the antidepressant effects of such drugs are attributable to reductions in the actions of pro-inflammatory cytokines." (PMID 30890971, 2019).
depression (continued). "Recent evidence suggests that stress hormones may actually facilitate inflammation followed by depression, through induction of various cytokines including IL-1, IL-6, IL-8, IL-18 and TNF (tumor necrosis factor)." (PMID 31150403, 2019). "Increased levels of IL-18 in plasma have been observed in patients with schizophrenia and moderate to severe depression, so a psychiatric comorbidity may have confounded plasma IL-18 levels in patients with AN." (PMID 30832404, 2019). "In a recent study IL-18 deficient mice showed a schizophrenia-like phenotype (higher impulsivity and aggression), but no relevant behavioral changes in tests for anxiety- (EPM) or depression-like behavior (FST)." (PMID 30975083, 2019). "Indeed, NLRP3 gene expression was found elevated in PBMCs of patients with major depression corresponding with elevated serum levels of IL-1β and IL-18, supporting the clinical applicability of inflammasome activation in depression." (PMID 31749681, 2019). "However, there is increasing experimental evidence linking stress, IL-18 and depression and in a complex manner." (PMID 29520075, 2018). "In T2D, IL-18 and IL-1RA were positively associated with depression for two scores (IL-18: PHQ-9, WHO-5; IL-1RA: CES-D, WHO-5), hsCRP was associated with one depression score (PHQ-9), and adiponectin showed an inverse association with one depression score (PHQ-9) after adjustment (P = 0.006–0.048)." (PMID 29520075, 2018). "In patients with psoriasis, depression severity correlated positively with psoriasis duration, the Psoriasis Area Severity Index, the percentage of body surface area affected by psoriatic lesions, and interleukin-18 concentration." (PMID 30092066, 2018). "For instance, like other pro-inflammatory cytokines, IL-18 may participate in the control of the activity of the HPA axis reported to be dysregulated in depression." (PMID 20113500, 2010). "Finally, IL-18 can affect other hallmarks of depression impairing learning and memory by acting as an attenuator of long-term potentiation, and inducing lethargy and loss of appetite." (PMID 20113500, 2010). "Furthermore, the sustained activation of the cGAS-STING pathway can also increase the production of ROS, leading to more mtDNA release, which further drives the secretion of IL-1β and IL-18 and affects ATP synthesis, impacting mitochondrial energy metabolism and mediating the onset of depression." (PMID 40699781, 2025). "It has been shown that IL-1β and IL-18 released upon the activation of NLRP3 inflammatory vesicles may be key molecules in triggering the immune response in depression and further exacerbate the pathological process through Gasdermin D (GSDMD)-mediated cellular pyroptosis response." (PMID 40497971, 2025). "Although animal studies have shown that abnormal IL-18 level may lead to changes in the structure of the hippocampus and the appearance of “depression” in mice, few studies have explored the relationship between IL-18 and brain functional activity in patients with depression." (PMID 35931995, 2022). "In addition, clinical data revealed increased peripheral (plasma) levels of IL-18 in patients with depression, while an experimental study described elevated neocortical IL-18 gene expression in animal model of stress and depressive behavior based on social defeat." (PMID 30610610, 2019). "Patients with major depressive disorder (MDD) display elevated serum levels of IL‐1β and IL‐18, accompanied by increased expression of the NLRP3 inflammasome and caspase‐1." (PMID 41556446, 2026). "IL‐18, TNF‐α, and the proinflammatory PC1 values positively correlated with AUD severity and anxiety/depression measures." (PMID 40317574, 2025). "IL‐18 positively correlated with AUDIT, ADS, OCDS, BSA and anxiety/depression measures, and TNF‐α positively correlated with ADS, AUDIT and STAI‐T." (PMID 40317574, 2025).
depression (continued). "Many compounds reduce IL-18 expression through the modulation of the NLRP3 pathway, resulting in attenuated depression-like behaviors." (PMID 38791125, 2024). "Ultimately, chronic stress significantly increases IL-18 in the HPC, PFC, HYP, and periphery, which can be reduced by various treatments that suppress the expression of the NLRP3 inflammasome and attenuate depression-like behaviors." (PMID 38791125, 2024). "Consistent with our findings, activation of the NLRP3 inflammasome was observed in AMI rats with depression, leading to the cleavage of GSDMD and subsequent release of IL‐18 and IL‐1β, thereby promoting microglial pyroptosis." (PMID 38970230, 2024). "In conclusion, exercise can improve depression by inhibiting inflammatory factors (e.g., TNF-α, IL-6, and IL-18) and promoting anti-inflammatory factor TGF-β1, inhibiting the inflammatory response." (PMID 37239191, 2023). "Serum IL-6, IL-8, IL-18, and IFN-γ are estimated biomarkers for depression and can identify the physiopathology of inflammatory regulation abnormalities in depression." (PMID 37637801, 2023). "We examined and confronted the ranges of IL-18, TGF-β, RANTES, ICAM-1, and uPAR among stable COPD patients, recurrent depressive disorder (rDD) patients, and healthy controls." (PMID 37921965, 2023). "The scope of this study was to measure and compare the profiles of IL-18, TGF-β, RANTES, ICAM-1, and uPAR among stable COPD patients, recurrent depressive disorder (rDD) patients, and healthy controls." (PMID 37921965, 2023). "In a meta-analysis that compared 5166 patients with depression and 5083 controls, patients with depression exhibited a significantly higher pro-inflammatory state (i.e., higher levels in CRP, L-3, IL-6, IL-12, IL-18, sIL-2R, and TNFα) than controls." (PMID 35682203, 2022). "Anxiety and depression behaviors were assessed by open field tests (OFT) and forced swimming tests (FST), while interleukin 18 (IL-18), 5-hydroxytryptamine (5-HT) and brain-derived neurotrophic factor (BDNF) were the molecular biomarkers of depression." (PMID 36422003, 2022). "In a meta-analysis studying inflammatory markers in depression (collecting 5166 patients with depression and 5083 healthy controls), the researchers found that IL-6, TNF-α, IL-12, IL-3, IL-18, and sIL-2R were elevated in depression group." (PMID 36408212, 2022). "The therapeutic effect of PAP on depression-like behaviors and its regulatory role on protein expressions of NF-κB, NLRP3, ASC, Caspase-1, GSDMD-N, Cleaved-IL-1β, and Cleaved-IL-18, etc., paved the way for us to understand PAP and its effect on pyroptosis." (PMID 35401226, 2022). "Furthermore, abnormal levels of IL-18 may also be related to the pathogenesis of depression." (PMID 35931995, 2022). "Antidepressants decreased IL-1β and IL-18 levels in serum and suppressed NLRP3 expression in MDD patients and mice with stress-induced depression." (PMID 36558541, 2022). "Thus, lower TTR of the PFC in Il18−/− mice might be a mediating factor of depression." (PMID 34708129, 2021). "We found increases in the mean levels of CRP, IL-3, IL-6, IL-12, IL-18, sIL-2R and TNF α in patients with depression." (PMID 32113908, 2020). "Our meta-analysis finds evidence that mean-scaled variability, measured as CVR, is reduced in patients with depression for CRP, IL-12 and sIL-2R, while it is unchanged for IL-3, IL-6, IL-18 and TNF α." (PMID 32113908, 2020). "IL-18 was the only inflammatory marker that correlated with the MADRS-S score and is consistent with other studies of inflammatory markers and depression." (PMID 31817800, 2019). "The levels of several inflammatory molecules, including NGFs, IL-18, and CST5, were altered in the plasma of patients with depression." (PMID 31817800, 2019). "IL-18 contributes to the development of depression by regulating the HPA axis and is recognized as a biomarker of psychological stress, with elevated levels detected in the blood of individuals with depression." (PMID 41194915, 2025).
depression (continued). "The correlations between biomarker levels (IL-18, IRE1, pERK, ATF6) and CECS scores (Anger, Depression, Anxiety subscales, and total score) reveal distinct patterns influenced by the presence and duration of PTSD, providing insights into the neurobiological and emotional dynamics of the disorder." (PMID 40806635, 2025). "Interestingly, in the combined sample, IL‐18, TNF‐α, and the proinflammatory PC‐1 values positively correlated with measures of AUD severity and anxiety/depression measures." (PMID 40317574, 2025). "CRP, C-reactive protein; GDS, Geriatric Depression Scale; IL-6, interleukin 6; IL-18, interleukin-18; MMSE, Mini Mental State Examination; NSAIDS, non-steroidal anti-inflammatory drugs." (PMID 41419753, 2025). "Furthermore, mangiferin downregulates the contents of IL-18, IL-1β, IL-6, and TNF-α in the hippocampus of the CUMS-induced depression mouse model by inhibiting the NLRP3/ASC/caspase-1 pathway." (PMID 38915473, 2024). "The increase of pro-inflammatory cytokines (interleukin (IL)-1β, IL-6, IL-18, and TNF-α) in individuals with depression may elicit neuroinflammatory processes and peripheral inflammation, mechanisms that, in turn, can contribute to gut microbiota dysbiosis." (PMID 38474387, 2024). "After 24 weeks of HFHSD exposure, male mice showed a general depression in the expression of cytokines, with prominent reduction of TNF-α, IL-6 and IL-13, but increased TGF-β, while female mice showed over-expression of IFN-γ and IL-18." (PMID 39302596, 2024). "Additionally, other pro-inflammatory cytokines showed similar outcomes in depression like IL-1β, TNF- α, and IL-18." (PMID 37957650, 2023). "Serum IL-18 concentration on day 7 was significantly higher in patients with post-stroke depression than in patients without post-stroke depression." (PMID 37509542, 2023). "A meta-analysis of cytokine alterations in the blood, based on 107 studies comprising a total of 5,166 patients with depression compared to 5,083 healthy controls, found levels of IL-3, IL-6, IL-12, IL-18 and TNF-ɑ to be higher in blood from the patients with depression." (PMID 37016363, 2023). "We were not able to detect a concurrent contribution of IL-1β and IL-18 to the likelihood of depression, possibly because of their involvement in the NLRP3-independent pathways." (PMID 37763063, 2023). "Higher levels of IL-18 are observed in the plasma of women suffering from depression during pregnancy than in pregnant women without symptoms of the disease." (PMID 37892657, 2023). "Higher levels of IL-18, TGF-β, RANTES, and uPAR in patients with COPD might indicate the presence of depressive disorder and suggest the need for further evaluation of the mental state of these patients." (PMID 37921965, 2023). "Similar to COPD, IL-18, TGF-β, RANTES, ICAM-1, and uPAR have been explored in depressive disorder." (PMID 37921965, 2023). "Interestingly, we observed the characteristic hallmarks of pyroptosis in depression, which included increased activation of NLRP3 inflammasome and the release of IL-1β and IL-18." (PMID 35496273, 2022). "The DC level in the left posterior cingulate gyrus showed a significant and negative correlation with IL-18 in depression patients." (PMID 35931995, 2022). "In addition, BHB induction attenuated expression of IL-18, IL-1β and NLRP3 inflammasome in a rodent model of depression." (PMID 36533180, 2022). "It was shown that dimethyl fumarate can reduce IL-1β, IL-18, caspase-1, and NLRP3 levels through the Nrf2/NF-κB signaling pathway, thus inhibiting LPS-induced microglial pyroptosis and disease manifestations in LPS-challenged depression mice." (PMID 35722622, 2022). "In the same sample, we also find that blood levels of CRP, IL-3, IL-6, IL-12, IL-18, sIL-2R and TNF α are significantly elevated in patients with depression with medium-large effect sizes (range 0.54–1.97), and that these findings are robust to a range of potential confounds and moderators." (PMID 32113908, 2020).
depression (continued). "In particular, tumor necrosis factor alpha (TNFα), interleukin-2 (IL-2), interleukin-6 (IL-6), interleukin-13 (IL-13), interleukin-18 (IL-18), C-reactive protein (CRP), chemokine-2 (CCL2), and chemokine-11 (CCL11) are elevated in depression based on multiple meta-analyses." (PMID 32351416, 2020). "Induction of sadness increased circulating IL-18 levels in individuals without and with depression, possibly mediated by μ-opioid system activation, while neutral mood induction reduced IL-1847–49." (PMID 29520075, 2018). "Compared to participants with mild depression and participants without depression, participants with moderate depression had higher serum concentrations of IL-6 and IL-18, and lower 25(OH)D3 concentrations." (PMID 30092066, 2018). "Depression severity correlated negatively with the 25(OH)D3 concentration and positively with psoriasis duration, the PASI, the percentage of body surface area affected by psoriatic lesions, and the interleukin-18 concentration." (PMID 30092066, 2018). "Only the IL-18 concentration differed significantly between these groups; compared with patients without depression, patients with moderate depression had significantly higher IL-18 concentrations." (PMID 30092066, 2018). "Previous studies showed that patients with depression and no clinically important inflammatory conditions had high concentrations of IL-6 and IL-18." (PMID 30092066, 2018). "Moreover, the administration of IL18 into the amygdala, but not the hippocampus, led to severe depression-like behaviors." (PMID 36151082, 2022). "In particular, serum IL-18 levels, but not that of IL-6 or TNF-α, measured 1 and 7 days after stroke were higher in patients that later developed depression." (PMID 23675319, 2013). "Thus, our results do not support the depression-inflammation hypothesis with respect to the biomarkers assessed (CRP, IL-18, IL-1-ra, albumin, fibrinogen)." (PMID 23967272, 2013).